FMNL2 (formin like 2)
Diseases named in the same sentence as FMNL2 in open-access papers (continued):
Sharing a sentence is not in itself a finding about the gene and the disease.
brain infarcts (1 paper, 2022). "The mediation analysis suggested an indirect effect, in which Aβ or tau deposition increased FMNL2 expression, which was then associated with brain infarcts (mediation effect: p = 0.002 amyloid; p < 2 × 10–16 tau)." (PMID 35608697, 2022). "A mediation model suggested that FMNL2 expression mediates the association of Amyloid-β and phosphorylated tau deposition with brain infarcts, although no direct association was observed between them." (PMID 35608697, 2022).
breast tumor (1 paper, 2023). "We find that phosphorylated FMNL2 drives TGFβ‐induced invasion of breast tumor cells by critically promoting secretion of the pro‐metastatic factor ANGPTL4." (PMID 36691769, 2023).
cognitive decline (1 paper, 2022). "This suggests that the biological role of FMNL2 and the cellular interactions between neuro-glio-vascular niche cells could be an early response to the disease and extends toward later stages even when cognitive decline manifests." (PMID 35608697, 2022).
colorectal adenocarcinoma (1 paper, 2010). The most common type of colorectal carcinoma. "The colorectal metastasis study illustrated the relative change of FMNL2 expression in normal colon and colorectal adenocarcinoma, especially metastatic disease." (PMID 20633255, 2010).
depression (1 paper, 2021). "FMNL2 has been identified in patients with depression and is the top hit in a GWAS on schizophrenia patients in Japan." (PMID 33671795, 2021).
Hypertension (1 paper, 2022). The presence of chronic increased pressure in the systemic arterial system. "Analyzing each risk factor of the CVRF separately, FMNL2 interacts most strongly with history of hypertension (p = 7.53 × 10–4) and BMI (2.51 × 10–3)." (PMID 35608697, 2022).
infarction (1 paper, 2022). A localised pathological necrosis of tissue resulting from obstruction of the blood supply usually by a thrombus, an embolus, or vascular torsion. "The expression level of FMNL2 was also significantly higher in those with gross chronic infarcts in cortex compared to those without infarctions (adjusted for age, sex, and processing factors β = 1.024, p FDR = 0.003)." (PMID 35608697, 2022).
inflammatory bowel disease (1 paper, 2021). A spectrum of small and large bowel inflammatory diseases of unknown etiology.
intracranial aneurysm (1 paper, 2022). "All genes except SYCP1 were expressed in intracranial aneurysm and control cerebral artery tissue, while FMNL2 and TBC1D2 showed high gene expression in these tissues, further prioritizing these genes." (PMID 35228681, 2022).
lung adenocarcinoma (1 paper, 2016). A carcinoma that arises from the lung and is characterized by the presence of malignant glandular epithelial cells. "In our study, we also demonstrated that ectopic expression of RMRP promoted the expression of KRAS, FMNL2 and SOX9 in lung adenocarcinoma cell, which were the direct taget gene of miR-206." (PMID 27906963, 2016). "In addition, our data showed that ectopic expression of RMRP promoted theexpression of KRAS, FMNL2 and SOX9 in lung adenocarcinoma cell." (PMID 27906963, 2016).
metastatic melanoma (1 paper, 2016). A melanoma that has spread from its primary site to another anatomic site. "The pan-FMNL2 immunoblot largely confirmed the qPCR results, with highest levels of FMNL2 expression in primary melanocytes and metastatic melanoma (A375 and WM266.4) and CRC (LS174T and SW620) cell-lines." (PMID 27578625, 2016).
Obesity (1 paper, 2025). Accumulation of substantial excess body fat. "These included IL1R1 (hypermethylated among lean), FMNL2 (hypermethylated in obesity) in OVAT and TSC22D1 (hypermethylated in obesity) in SAT." (PMID 41225618, 2025). "Further, we investigated in more detail selected DMRs in TSC22D1, HAS2, GCC1, NCKIPSD from SAT, all being hypermethylated in individuals with obesity and BCCIP, IL1R1 (hypermethylated in lean) and FMNL2 (hypermethylated in individuals with obesity) from OVAT." (PMID 41225618, 2025).
osteoporosis (1 paper, 2024). A condition of reduced bone mass, with decreased cortical thickness and a decrease in the number and size of the trabeculae of cancellous bone (but normal chemical composition), resulting in increased fracture incidence. "Further analysis using single-cell data allowed us to identify two key genes, FMNL2 and SRBD1, that are closely linked to both osteoclasts and osteoporosis." (PMID 38883609, 2024). "Particularly, future studies on genes like FMNL2 may reveal their specific roles and therapeutic potential in osteoporosis." (PMID 38883609, 2024). "The analysis identified two key genes, FMNL2 and SRBD1, as playing pivotal roles, and found that the gut microbiome indirectly influences osteoporosis by regulating these genes." (PMID 38883609, 2024).
postmenopausal osteoporosis (1 paper, 2024). Metabolic disorder associated with fractures of the femoral neck, vertebrae, and distal forearm. "Furthermore, our research has identified several key genes (FMNL2 and SRBD1) whose expression in osteoclasts is significantly associated with the risk of postmenopausal osteoporosis." (PMID 38883609, 2024). "Additionally, key genes FMNL2 and SRBD1 were identified, offering new therapeutic strategies for the treatment of postmenopausal osteoporosis." (PMID 38883609, 2024).
proteinopathies (1 paper, 2022). "The role of FMNL2 may also be required in other proteinopathies such as progressive age-related tauopathy, and FMNL2 is also upregulated and delineated in blood vessel structures." (PMID 35608697, 2022).
Stroke (1 paper, 2011). Sudden impairment of blood flow to a part of the brain due to occlusion or rupture of an artery to the brain. "Replication studies, particularly in young stroke cases, are required to assess the role of rs2304556 and/or other variants in and around FMNL2 with young-onset stroke." (PMID 22384361, 2011). "Although no single SNP reached genome-wide significance (P < 5 × 10−8), we identified two SNPs in chromosome 2q23.3, rs2304556 (in FMNL2; P = 1.2 × 10−7) and rs1986743 (in ARL6IP6; P = 2.7 × 10−7), strongly associated with early-onset stroke." (PMID 22384361, 2011).
cancer (25 papers, 2010 to 2024). A tumor composed of atypical neoplastic, often pleomorphic cells that invade other tissues. "FMNL2 also plays an important role in cell migration and is involved in metastasis of several cancers, such as colorectal cancer where it is associated with aggressive tumor development, hepatocellular carcinoma and gastric cancer." (PMID 36979484, 2023). "Dysregulation of FMNL2 has been discovered in several types of cancers and is associated with the development of aggressive tumors." (PMID 29881327, 2018). "At least four alternatively-spliced FMNL2 isoforms are expressed in primary melanocytes as well as in specific cancer cell-lines and sequence analysis of the encoded proteins suggests they will be targeted by distinct regulatory pathways." (PMID 27578625, 2016). "Formin-like protein 2 (FMNL2) belongs to a highly conserved family of cytoskeletal remodeling proteins that have been reported to be implicated in various actin-dependent physiological and cancer-associated processes." (PMID 35379791, 2022). "Given all these considerations, it will be interesting to analyze the role of FMNL2 in inducible exosome secretion at the IS in T lymphocytes, but also the role of FMNL1β in exosome secretion by cancer cells during cell invasion." (PMID 39479958, 2024). "The actin nucleating and polymerizing formin-like 2 (FMNL2) is upregulated in several cancers and has been shown to play important roles in cell migration, invasion, cell–cell adhesion and filopodia formation." (PMID 36979484, 2023). "Protein kinase C (PKC)‐dependent phosphorylation of FMNL2 downstream of TGFβ stimulation is required for cancer cell invasion as well as ANGPTL4 vesicle trafficking and secretion." (PMID 36691769, 2023). "Comparing the expression of FMNL2 in the normal tissues and cancer tissues, not only the stages 1, 2, 3, and 4 have the great difference to the normal tissues, but also the FMNL2 has the difference between stage 2 and stage 3." (PMID 36124068, 2022). "Previous studies have shown that FMNL2 binds directly many actin bundling proteins, such as fascin and cortactin, then facilitates cancer cell migration." (PMID 36335129, 2022). "MiR-34a also behaves as a tumor suppressor in CRC by inhibiting cancer cell proliferation, invasiveness and metastasis through the down-regulation of formin like 2 (FMNL2) and E2F transcription factor 5 (E2F5) expressions." (PMID 30227605, 2018). "As a member of the diaphanous-related formin subfamily, FMNL2 has been proposed to be involved in cancer metastasis through TGF-β1/Smad signalling." (PMID 28198387, 2017). "In accordance with our recent study, DIO1 expression resulted also in suppression of TGFBI, and several other proteins (e.g. PODXL, CD74) that promote RCC progression or act as oncogenic proteins in other cancers (e.g. FMNL2, APBB1IP, ASAP1, and LRRFIP1)." (PMID 29272308, 2017). "Our preliminary transcription analysis indicates that FMNL2 expression is up-regulated in several forms of cancer, and future studies will be directed to find the ones where this difference has biological and medical relevance." (PMID 20633255, 2010). "Other exosomal proteins have also been identified as important predictive biomarkers of GIC owing to create cancer-friendly condition to promote cancer metastasis, like exosomal Formin-like 2 (FMNL2), cytotoxic T lymphocyte antigen 4 (CTLA-4), RAB5A, aspartate β-hydroxylase, and so on." (PMID 38561768, 2024). "In summary, we report a novel role for FMNL2 in vesicular actin dynamics that contributes to a pro‐invasive programme and may promote the progression of cancers." (PMID 36691769, 2023). "However, to our knowledge, the role of formin-like protein 2 (FMNL2) in the progression of various types of cancers was still under debate." (PMID 35379791, 2022). "Thus, FMNL2 drives β1-integrin internalization and invasive motility of cancer cells in a phosphorylation-dependent manner." (PMID 31751425, 2019).
cancer (continued). "Dysregulation of FMNL2 has been discovered in cancers and is closely related to cancers." (PMID 29881327, 2018). "FMNL2 expression is also required for invasive cell motility in other cancer cell-lines." (PMID 27578625, 2016). "Since miR-206 is multifunctional, mechanisms by which LINC00707 affects cancer cell functions involves various miR-206-target mRNAs; NOTCH3 controls cell proliferation, and formin-like 2 regulates cell migration." (PMID 37784093, 2023). "In human cancers, miR-137 can modulate the expression of a multitude of genes, including EZH2, FMNL2, and Paxillin." (PMID 24970808, 2014). "Other formins, (i.e., mDia1, Formin-like 2, FHOD, FRL1/FMLN1) also drive membrane blebbing and amoeboid cancer cell motility in vitro, suggesting a conserved role for formins in regulating morphological plasticity during cancer cell motility." (PMID 23024796, 2012). "At this point, we conclude that normal colorectal mucosa does express FMNL2, but do not compare the level of expression to cancer." (PMID 20633255, 2010).
tumor (16 papers, 2013 to 2024). "Mechanically, circ_001569 acts as a miRNA sponge to directly inhibit miR-145, and subsequently up-regulates miR-145 targets E2F5, BAG4 and FMNL2 to exert its tumor promoting function in CRC cells." (PMID 27058418, 2016). "FMNL2 (formin like protein 2) is included in tumor cell migration and EMT." (PMID 34298612, 2021). "Formins, which are potent regulators of actin dynamics, may be involved in tumor invasion and metastasis promotion; and emerging evidence has already implicated FMNL1, FMNL2, and FMNL3 in these processes." (PMID 31861134, 2019). "Literature research shows that FMNL2 has a close relationship with tumor metastasis." (PMID 29881327, 2018). "Second, FMNL2 also modulates EMT which is an important phenomenon contributing to tumor metastasis." (PMID 29881327, 2018). "Thus, circ_001569 acts as a miRNA sponge to directly combine with miR-145, and subsequently up-regulates miR-145 targets E2F5, BAG4 and FMNL2 to exert its tumor promoting function in CRC cells." (PMID 27058418, 2016). "Additional research demonstrated that FMNL2 enhanced the ubiquitin-mediated proteasome degradation of COMMD10, hence reducing the nuclear translocation of NF-κB subunit p65 and promoting tumor progression." (PMID 36776284, 2023). "In our SCC cell lines, FMNL2 expression was not altered suggesting a tumour/tissue specific control of formin expression in EMT." (PMID 24086398, 2013).
FMNL2 also shares sentences with these, for which no sentence is quoted: Alzheimer disease (1 paper); autism (1); autism spectrum disorder (1); bladder cancer (1); clear cell renal cell carcinoma (1); epilepsy (1); facioscapulohumeral muscular dystrophy (1); fibrosarcoma (1); glioma (1); ischemic stroke (1); metastatic colorectal cancer (1); metastatic disease (1); nasopharyngeal carcinoma (1); ovarian carcinoma (1); pancreatic cancer (1); primary open-angle glaucoma (1); schizophrenia (1); thyroid cancer (1).